AURKAIP1 (aurora kinase A interacting protein 1)
Description:
May act as a negative regulator of Aurora-A kinase, by down-regulation through proteasome-dependent degradation.
Synonyms: MRP-S38; AIP; AKIP; Cox24; FLJ20608; mS38
Tractability: Small molecule: a structure with a bound ligand is known; it belongs to a druggable protein family. PROTAC: ubiquitination databases record sites on it; a small molecule that binds it is known.
Target class: Other cytosolic protein
Gene: Protein-coding gene on chromosome 1 (1,373,729 to 1,375,521, reverse strand). Ensembl gene ENSG00000175756.
Subcellular location: Mitochondrion matrix; Nucleus
Subcellular location (Human Protein Atlas): Mitochondria; Nucleoplasm
Pathways (Reactome):
Metabolism of proteins: Mitochondrial ribosome-associated quality control; Mitochondrial translation elongation; Mitochondrial translation initiation; Mitochondrial translation termination
Gene Ontology:
Molecular function: protein binding
Biological process: positive regulation of proteolysis; mitochondrial translation
Cellular component: mitochondrial matrix; mitochondrion; nucleoplasm; nucleus; mitochondrial inner membrane; mitochondrial small ribosomal subunit
Genetic constraint (gnomAD): Loss-of-function variants: 20 observed, 13.23 expected, observed/expected ratio (o/e) 1.51, 90% interval 1.05 to 1.92. The synonymous counts are far from expectation, so gnomAD's model fits this gene poorly and the ratio says little. Missense variants: 319 observed, 241.35 expected, observed/expected ratio (o/e) 1.32, 90% interval 1.21 to 1.45. Synonymous variants: 156 observed, 106.48 expected, observed/expected ratio (o/e) 1.47, 90% interval 1.28 to 1.67.
Homologues: Orthologues: chimpanzee AURKAIP1 (99% identical), macaque AURKAIP1 (92% identical), dog AURKAIP1 (73% identical), guinea pig AURKAIP1 (72% identical), pig AURKAIP1 (71% identical), mouse Aurkaip1 (69% identical), tropical clawed frog aurkaip1 (42% identical), zebrafish aurkaip1 (42% identical).
Diseases named in the same sentence as AURKAIP1 in open-access papers:
AURKAIP1 is named in the same sentence as 8 diseases in open-access papers, as found by Europe PMC text mining. Sharing a sentence is not in itself a finding about the gene and the disease. The quoted sentences say what the papers report.
breast carcinoma (1 paper, 2023). "Since DDX5 has been elucidated to have a well-defined mechanism of action in tumors including breast cancer by reviewing the literature, we established DDX5 as a reciprocal target and further examined whether AURKAIP1 fostered TNBC development via the DDX5 mediator." (PMID 38040691, 2023).
triple-negative breast carcinoma (1 paper, 2023). An invasive breast carcinoma which is negative for expression of estrogen receptor (ER), progesterone receptor (PR), and human epidermal growth factor receptor 2 (HER2). "The expression levels of AURKAIP1 were detected in triple negative breast cancer (TNBC) by immunohistochemistry and western blots." (PMID 38040691, 2023).
tumor (3 papers, 2022 to 2025). "Then a tissue microarray (TMA) containing 100 TNBC samples was used to verify the association of AURKAIP1 expression with age, menopause status, tumor grade, T stage, N stage and TNM stage." (PMID 38040691, 2023). "Treatment of AURKAIP1 with siRNA reduced tumor growth, which portended that AURKAIP1 was essential for tumorigenesis and aggressiveness of TNBC." (PMID 38040691, 2023). "From the results, we found that AURKAIP1 was explicitly upregulated in TNBC, which was positively associated with tumor size, lymph node metastases, pathological stage and unfavorable prognosis." (PMID 38040691, 2023). "In the current study, we revealed, for the first time, the critical function of AURKAIP1 in tumor progression of TNBC in vitro and in vivo." (PMID 38040691, 2023). "After summarizing the current analysis results and the reported literatures, we finally determined AURKAIP1 for exploring its role in tumor progression of TNBC." (PMID 38040691, 2023). "In particular, TNBC patients with high AURKAIP1 expression tended to have larger tumor, more axillary lymph node metastasis and severer clinical stage." (PMID 38040691, 2023). "Up to this point, these findings indicated that AURKAIP1 might be capable of a novel tumor-promoting role in TNBC, which suggested for the first time that AURKAIP1 did have a distinct role in human cancer which did not rely upon the Aurora-A regulation." (PMID 38040691, 2023). "Further, the expression of NDUFB7, AURKAIP1, ROMO1, SCAND1, GADD45GIP1, and NDUFA13 was upregulated in the four tumor subtypes compared with normal adjacent tissue." (PMID 34996995, 2022).
cancer (1 paper, 2022). A tumor composed of atypical neoplastic, often pleomorphic cells that invade other tissues. "AURKAIP1 has been identified as a valuable feature It has been shown that AURKAIP1 promotes Aurora-A, an oncogene, the overexpression of which attributes to aneuploidy and could lead to cancer potentially." (PMID 35955705, 2022).
neurological disease (1 paper, 2019). "SFN is located at the center of an interaction network of proteins including HYAL2, NBEA, NBR1, AURKAIP1, RALGPS2, and SLC1A2, some of which have known involvement in brain function and neurological disease." (PMID 31029150, 2019).
AURKAIP1 also shares sentences with these, for which no sentence is quoted: acute myeloid leukemia (1 paper); osteosarcoma (1); primary sclerosing cholangitis (1).